IFNG (interferon gamma)
Diseases named in the same sentence as IFNG in open-access papers (continued):
Sharing a sentence is not in itself a finding about the gene and the disease.
tumor (continued). "Our data suggest that the increased production of IFNγ in NK cells exposed to cetuximab and radiated tumor cells may contribute to activation of CD8+ T cells, as this effect that was dependent upon antibody and FcγR expression." (PMID 33281820, 2020). "Besides, Munich and colleagues used murine BMDC DEVs loaded with TNF, FasL and TRAIL describing that these vesicles had the ability to directly kill B16 tumor cells ex vivo by promoting apoptosis, and also induced NK cell activation and their IFNγ production." (PMID 33260499, 2020). "In the K7M2 osteosarcoma model, IL-18 seems to be implicated in MDSC recruitment at the tumor site and the association of anti-PD-1 with IL-18BP (an inhibitor of IL-18) increases the proportion of CD8+ IFNγ+ GzmB+ T cell tumor infiltration, and decreases tumor weight." (PMID 33261061, 2020). "Similarly, neutralization of IFNγ resulted in increased tumor growth comparable to anti-PD-1/G007-LK -treated mice." (PMID 32332858, 2020). "Interferon-gamma (IFN-γ) is released by activated T-cells after interaction with tumor antigens." (PMID 32867025, 2020). "Co-cultures of CD8+ T cells with autologous CD45― tumor containing cells demonstrated cytotoxicity (p = 0.030) and IFNγ production (p = 0.003) that inversely correlated with percent of myeloid derived suppressor cells, lactate, and lactate dehydrogenase (LDH) within the MPE." (PMID 32867034, 2020). "The antitumor activity was measured by tumor cell killing and IFNγ production in co-cultures." (PMID 32642679, 2020). "Upon tumor cell recognition, NK cells release the content of their cytotoxic granules by a process called degranulation and produce pro-inflammatory cytokines like IFNγ." (PMID 33123121, 2020). "The combination of peritumoral FlaB-Vax delivery with PDT effectively induced a systemic and local response of peptide tumor antigen-specific IFNγ-secretions and accumulation of effector memory CD8+ T cells, which further enhanced PD-1 blockade therapeutic outcome." (PMID 33171765, 2020). "Anti-tumor activity by these cells was supported by IFNγ expression and signaling." (PMID 33584714, 2020). "Furthermore, in tumor tissue supernatants from Rag2−/− mice, IFNγ and IL-17A were significantly increased, while IL-10 was significantly decreased." (PMID 33042110, 2020). "In addition, we observed that the tumor-infiltrated OT1-iT cells (CD45.2+CD8+) secreted interferon gamma (IFNγ) and granzyme B (GzmB), which indicated their tumor cell killing behavior." (PMID 32669292, 2020). "Therefore, to further examine the direct role of these cytokines in the tumor microenvironment, recombinant IFNγ or IL-17A were injected peritumoraly three times a week for up to 4 weeks." (PMID 33042110, 2020). "An increasing amount of evidence reported that CD8+ T cells in the tumor microenvironment could produce IFNγ, leading to the upregulation of the PD-1/PD-L1 axis and IDO1." (PMID 32346613, 2020). "IDO1 was predominantly expressed in endothelial cells within the tumor microenvironment, and its expression in tumor endothelium was positively correlated to T-cell infiltration and to increased intratumoral expression of IFNγ." (PMID 32231867, 2020). "Similarly, within the CD8+ T cell compartment, those at the tumor were also more activated, expressing high levels of Ifng (interferon γ [IFNγ]), Prf1 (perforin), and Gzmb (granzyme B)." (PMID 32433953, 2020). "IFNγ can also promote apoptosis of tumor-reactive CD8+ T cells." (PMID 32517213, 2020). "We also cultured mouse and human Teff cells in conditioned medium and assessed the expression of effector molecules, including granzyme B, tumour necrosis factor alpha (TNF-α) and interferon gamma (IFN-γ), all of which are important in mediating the tumour-cell-killing activity of Teff cells." (PMID 32694789, 2020). "Analysis of tumor cytokines showed that IFNγ expression was highly regulated within the TME." (PMID 33584714, 2020).
tumor (continued). "Guadecitabine treatment increased both CD8a and IFNγ at the tumor site." (PMID 32106810, 2020). "Moreover, the autologous infusion of tumor antigen specific CD4+ Th1 lymphocyte can promote senescence in pancreatic tumor cells by releasing SASP factors such as IFNγ and TNFα." (PMID 32370259, 2020). "IFNγ is capable of inhibiting tumor angiogenesis by hampering the proliferation of ECs." (PMID 31256327, 2020). "In PDA animal models, we identified that either engineered or endogenous intratumoral tumor antigen-specific T cells also become defective in their production of IFNγ, TNFα and expression of cytolytic molecules including Granzyme B following specific peptide recognition." (PMID 33584701, 2020). "Infiltrating T lymphocytes, such as cytotoxic CD8+ T cells, may induce adaptive immunity resistance by upregulating PD-L1 via effects on IFNγ to inhibit anti-tumor immunity." (PMID 33339860, 2020). "Surprisingly, the tumor suppressive role of the IL33-ST2 signaling pathway occurred independently of MC abundance, but was mediated by mesenchymal (stem) cells and associated with a strong interferon gamma (IFNγ) gene expression signature." (PMID 32719677, 2020). "Given an established role for IL-18 and IL-27 in stimulating optimal IFNγ production and Th1 responses, our data suggest that increased tumor burden in the mice receiving AdIL-17A-transduced 4T1 cells could be due to the progressive loss of Th1 immunity." (PMID 32770025, 2020). "Here, in pooled analyses with TCLs/TCLs + IFNγ and FTDs (n = 177), the proportion of tumor-reactive CD4+ TILs was similar across all cohorts, and tumor-specific CD4+ T cell responses were detected in over 50% of patients in each clinical cohort (range 58% in OC to 71% in RCC)." (PMID 33198174, 2020). "Loss of IFNγ responsiveness in tumor cells may result from inactivating mutations in JAK1/2 disrupting INFγ signaling, leading to tumor immune escape and disease progression." (PMID 32992658, 2020). "On the other hand, IFNγ may also exert the opposite effect by modulating resistance of tumor cells to immune response." (PMID 32517213, 2020). "Of these, IFNγ produced by TILs as a result of T-cell recognition of tumor antigens is the most potent inducer of non-constitutive PD-L1 expression in cancer cells, and in the tumor microenvironment." (PMID 32992658, 2020). "Moreover, interferon-gamma (IFN-gamma) can protect against tumor development, affecting both innate and adaptive host immune responses." (PMID 32422889, 2020). "Furthermore, the changes in CD4+ and CD8+ T cell cytokines produced in the tumor microenvironment after G-CSFR−/− cell injection led us to test the ability of IFNγ or IL-17A alone to inhibit tumor growth." (PMID 33042110, 2020). "Interestingly, by inhibiting tumor derived IFNγ and decreasing the immune stimulated genes in tumor cells, IFNγ production by T cells was increased, promoting tumor cell killing." (PMID 32133005, 2020). "For example, an increase in IFNG within a tumor may reflect increased IFN-γ production by T cells already within tumors or an increase in T cell infiltration into the tumor." (PMID 32657757, 2020). "miRNA modulation through the genetic deletion in macrophages of DICER, an enzyme fundamental for miRNA synthesis, was shown to inhibit tumor growth in preclinical models of breast, colon and lung tumors, reprogramming TAMs to express IFNγ and activate STAT1 proinflammatory signaling." (PMID 32708142, 2020). "Notably, the frequency of circulating IFNγ-producing cells in all groups correlated with therapy outcome in terms of tumor size and mice survival." (PMID 32290265, 2020). "IL-12 enhances cytotoxic T and NK cell activity while reversing tumor-induced immunosuppression, inhibiting angiogenesis, increasing lymphocyte trafficking and antigen presentation either directly or through induction of IFNγ." (PMID 33178203, 2020).
tumor (continued). "Similarly, T helper type 1 (Th1) cells also produce IFNγ and subsequently activate IFNγ gene signature which is primarily responsible for activating an anti-tumor immune response including an increase of infiltrated cytotoxic T cells in the TME." (PMID 32544882, 2020). "In addition, the existence of a negative feedback loop has been reported, whereby PD-L1 is expressed on the tumour surface by T cell activation and IFNγ production, and T cell activity is suppressed via PD-L1." (PMID 31914969, 2020). "This may be due in part to secretion of IFNγ from tumor specific T-cells within the tumor microenvironment." (PMID 33193345, 2020). "Recent studies showed that the single A2AR blockade or the combination with either PD-1/PD-L1 or CTLA-4 mAbs induces T-cell proliferation, enhances the expression of IFNγ and granzyme B by tumor-infiltrating CD8+ T-cells, thus restraining the tumor growth in preclinical models." (PMID 32760402, 2020). "Indeed, the TNC knockout tumours had more CD4+ and CD8+ TIL cells and more activated cytotoxic T cells (IFNγ+CD4+ and IFNγ+CD8+) in their TILs than the control tumours." (PMID 32732922, 2020). "However, co-stimulation of IFNγ and IL-21 provides conditions for protumorigenic M2 macrophages, which further expedite the tumor progression." (PMID 33505964, 2020). "The overall balance and timing of IFNγ expression over the course of tumor development and the downstream consequences likely critically determine an effective vs. suppressive immune response and an immunologic profile of consideration for immunotherapeutic approaches to treatment." (PMID 32265897, 2020). "Moreover, the NK cells that remained at the tumor site showed lower levels of cytolytic activity, as these cells expressed similar levels of IFNγ and lower levels of granzyme B compared to those in peripheral blood." (PMID 32117733, 2020). "Although NK cells isolated from tumor-bearing mice lost their ability to produce IFNγ almost completely compared with that of normal mice, NK cells from RQ-15986-treated tumor-bearing mice completely recovered IFNγ-producing ability." (PMID 32210957, 2020). "Tumor cells have developed adaptive immune resistance to avoid antitumor immune responses, which relies on PD-L1 expression stimulated by inflammatory signals such as interferon gamma (IFN-γ) secreted by activated tumor-infiltrating cells." (PMID 32992737, 2020). "In addition, the increased expression of IFNγ and granzyme B, as well as a three-fold increase in tumor-infiltrating CTLs, was observed." (PMID 32224883, 2020). "Taken together, this data suggest that disruption of lymphatic Nr2f6 converts tumor-infiltrating T cells into IFNγ- and IL-2-hypersecreting effector cells, apparently sufficient to prime the TIME for immune checkpoint therapy to more effectively control tumor growth." (PMID 31937317, 2020). "Since high density of cytotoxic CD8+ and IFNγ CD3+ T cells at the invasive margin is associated with better outcomes, the local accumulation of Tregs at this site might dampen the anti-tumor activity." (PMID 32937953, 2020). "This may explain the previously noted positive correlation between IL-32 expression and individual genes indicative of lymphocyte infiltration, such as CD3E, CD8A, and IFNG, in bulk tumor samples." (PMID 32841222, 2020). "In terms of de novo T-cell priming, CDCs and TLR-P DCs as well as the LPS/IFNγ DCs, which served as a positive control, were able to induce tumor-antigen-specific CD8+ T-cells at similar frequencies with a trend for higher proliferation of T-cells in the TLR-P group." (PMID 32100075, 2020). "In cord blood derived HSPC-generated humanized mouse model, PD-1 blocking (using nivolumab) inhibited the growth of MDAMB-231 tumor cells and CRC172 tumor cells by enhancing anti-tumor T cell response, increasing GrB+ or IFNγ+ CD8+ cells in tumors and reducing frequency of Treg and myeloid cells." (PMID 33603749, 2020).
tumor (continued). "We interpret these data to suggest that it may be critical for tumors to prevent any significant IFNγ secretion by tumor-specific T cells, since this could result in MHCI upregulation and permit a higher avidity interactions." (PMID 32355214, 2020). "Furthermore, these altered M2-like macrophages were able to cause a significant increase in the levels of IFNγ produced from co-cultured CD4+ T cells, and also significantly increased granzyme B release from CD8+ T cells in response to tumor cells." (PMID 32455916, 2020). "For that purpose, we performed an in vitro lysis assay using Pt#006-T cells as targets of pt#006 PRE, P1, P2, and P3 PBMC samples boosted in vitro either with the vaccine cells lysate, autologous tumor cells lysate or peptides that stimulated IFNγ production in the ELISPOT assays." (PMID 32582212, 2020). "IFNγ is a primary driver of PD-L1 expression on MOC1 tumor cells." (PMID 32633234, 2020). "The type II IFN IFNγ was also evaluated for enhancing 5-FU’s anti-tumor activity." (PMID 32575843, 2020). "Taken altogether, these observations suggest that a sizeable portion of tumor-specific CTLs could acquire CpG hypermethylation of their IFNγ promoter." (PMID 32194559, 2020). "Our results provide evidence that the anti-tumor effect of combined tankyrase and checkpoint inhibitor treatment against B16-F10 tumors is dependent on both IFNγ and CD8+ T cells and occurs, at least in part, through direct suppression of WNT/β-catenin signaling within the tumor cells." (PMID 32332858, 2020). "Specific SNPs in STAT4 and IFNG could be key for the promotion of the IL-12 pathway anti-tumor actions in NK, macrophages and T cells." (PMID 32973967, 2020). "TIL can boost PD-L1 expression in tumour cells in an interferon-gamma (IFN-γ)-dependent manner." (PMID 31992245, 2020). "Similarly, in the AT3 model, NAM treatment was associated with increased tumor infiltration by CD4+ T cells expressing TNF alone, TNF and IFNG, as well as TNF, IFNG, and IL2." (PMID 32732875, 2020). "Cumulatively, these data demonstrated that PD-L1 CAR haNKs can also mediate PD-L1-dependent tumor growth inhibition in immunodeficient mice bearing human HNSCCs, possibly through the ability of PD-L1 CAR haNKs to induce IFNγ-dependent PD-L1 expression on tumor cells." (PMID 32633234, 2020). "Overall, the dimeric architecture of the IFNγ/IFNGR1/IFNGR2 complex is critical for inducing the full spectrum of IFNγ-mediated pleotropic activities, which includes macrophage activation, tumor surveillance, and protection from intracellular pathogens, including mycobacteria." (PMID 33281831, 2020). "IFNγ or CD8 depletion abrogated the anti-tumor effect of PD-L1 CAR haNKs." (PMID 32633234, 2020). "Also, a higher frequency of CD8+ T cells expressing IFNγ was found in tumor and spleen of mice receiving Pmel T cells treated with ASO-Ddit3." (PMID 30894532, 2019). "Importantly, systemic injection of an IFNγ IFNγ-neutralizing antibody abolished the efficacy of the combination therapy with CDDP plus (R)-crizotinib in all transplantable tumor models investigated here (TC1 or MCA205 tumors, subcutaneous or orthotopic)." (PMID 30940805, 2019). "To assess if upregulation of activated PI3K was responsible for the OGD-associated effects on IFNγ signaling we tested whether pharmacological inhibition of PI3K could restore the sensitivity of the tumor cells to respond to IFNγ." (PMID 31196219, 2019). "IDO1 differentially expressed in tumor cells and its expression could be induced with interferon gamma (IFN-γ)." (PMID 31324754, 2019). "The tumor growth inhibition correlates with increased CD8 IFNγ+ tumor infiltrating T cells." (PMID 30736857, 2019). "Once the tumor antigen is recognized, PD-L1 could be upregulated by interferon gamma (IFNγ), which is generated by TILs at the tumor site." (PMID 31640203, 2019). "Pro-tumor: CLL cells induce ILC1s produce IFNγ and TNFα and form immunosuppressive environment." (PMID 32117199, 2019).
tumor (continued). "In addition, the activation and maturation of CD8+ T-cells is also modulated by IFNγ secreted by CD4+ Th1 cells and specific tumor-associated antigens processed by dendritic cells." (PMID 31430935, 2019). "In addition, CT treatment also elevated the expression of granzyme B, perforin, and IFNγ in the tumors, thus, demonstrating CT promotion of a Th1-polarized tumor microenvironment critical for combatting tumors." (PMID 30972427, 2019). "E7 specific IFNγ secreting CD8+ T cells cannot be detected from the tumour by ELISPOT assay." (PMID 31183361, 2019). "Providing an infusion of autologous tumor-specific CD8 T cells manipulated to express an effector (IFNγ-proficient) program could be a way to fight cancer and induce TAM reprogramming." (PMID 31766350, 2019). "Besides, a clinicopathological study on 64 PCNSL patients shows that the PD-L1 protein is detected in tumor microenvironments than in tumor cells and is correlated with expression of interferon-gamma (IFN-γ) and CD4 with OS16." (PMID 31292525, 2019). "Similarly, all but the FR-negative HOS-143b tumor cells triggered high levels of IFNγ, IL-2, and TNFα production after 44 h of co-culture at an E/T ratio of 1:1 with E2-CAR-T cells." (PMID 30941303, 2019). "However, pre-treatment of OVA-transduced YUMM1.1 tumor cells with IFNγ to induce H-2Kb expression and presentation of the OVA peptide SIINFEKL, sensitized them to OT-I T cell killing." (PMID 30718660, 2019). "In addition to their tumor targeting, these tumor-specific CTLs also showed better effector functions, such as IFNγ production and degranulation capacity." (PMID 30863405, 2019). "It is not yet to know whether the IL-9 secreting T cells in low dose DCG spore treated mice are contributing the antitumour effect, as IFNγ has been shown to be critical for rejecting the tumour." (PMID 31183361, 2019). "Pancreatic xenograft tumors also confirmed that the IFNγ and gemcitabine combination could significantly inhibit tumor growth in mice." (PMID 30782607, 2019). "Although Tfh differentiation may divert T cells from more efficient (e.g., IFNγ-producing) anti-tumor differentiation, it provides support for the tantalizing possibility that tumor-elicited B cell responses could be exploited against cancer." (PMID 31801070, 2019). "Studies analyzing PD-L1 expression on tumor cells following irradiation also demonstrated that this upregulation could be mediated by IFNγ, which is produced by T cells." (PMID 30941308, 2019). "Finally, as observed in human colorectal patients, anti-PD-1 therapy had a strong response to a microsatellite-high CRC PDX that correlated with a higher number of human CD8+ IFNγ+ T cells in the tumor." (PMID 30736857, 2019). "In the tumors with the highest IC expression and absent TC expression an association with reduced IFNγ downstream signaling in tumor cells was observed." (PMID 31125352, 2019). "As expected, the tumor growth was significantly diminished in the anti-PD-1 arm, which was associated with an increase in the presence of secreted IFNγ in the TME when compared to the no treatment group." (PMID 30992475, 2019). "IFNγ exerts anti-tumor function mainly through JAK2 signaling." (PMID 30948928, 2019). "Importantly, T cell produced IFNγ not only engages its receptor signaling on surrounding TAM but also on tumor cells themselves." (PMID 31766350, 2019). "IFNγ, IL-1β, tumor TNFα, TGFβ, IL-6, and IL-18 are key to the functionality of TAM." (PMID 31430935, 2019). "In addition to promoting tumor killing, IFNγ also upregulates PD-L1 expression on tumor cells, which, in turn, inhibits the effector function of CTLs by interacting with PD1 on CTLs." (PMID 30972427, 2019). "Anti-tumor: ILC1s in response to IL-12, produce IFNγ and TFNα to limit tumor growth." (PMID 32117199, 2019). "However, by intracellular FACS analysis we detected increases of TNFα and IFNγ expression in tumor infiltrating cells." (PMID 31214164, 2019).